PBX3 (PBX homeobox 3)
Diseases named in the same sentence as PBX3 in open-access papers (continued):
Sharing a sentence is not in itself a finding about the gene and the disease.
prostate carcinoma (12 papers, 2011 to 2024). A carcinoma that arises from epithelial cells of the prostate gland. "Current literature on PBX3 is known to be a functionally significant TF in a range of cancers, including prostate cancer, and linked to shorter overall survival; and the miR inhibitor of PBX3, miR-let-7d, is regulated by androgen." (PMID 34867780, 2021). "Moreover, elevated expression of PBX3 is associated with indolent progression to castration-resistant prostate cancer." (PMID 32047817, 2020). "For example, in prostate cancer, PBX3 was found to be upregulated in prostate cancer and directly regulated by miR-let-7d." (PMID 35509064, 2022). "There is also evidence for the regulation of PBX3 expression by androgen signaling in prostate cancer." (PMID 32069812, 2020). "This includes prostate cancer, in which PBX3 is expressed at higher levels in malignant compared to benign diseases, with the androgen-regulated miR inhibitor of PBX3, miR-let-7d, showing the opposite trend." (PMID 32069812, 2020). "PBX3 has been reported to be over-expressed in prostate cancer, whilst FANCG belongs to a group of proteins known as the Fanconi anemia complementation family and has been reported to be important in DNA damage repair pathways." (PMID 23737949, 2013). "PBX3 was up-regulated and Let-7d was down-regulated in prostate cancer compared to normal epithelial prostate cells." (PMID 21548940, 2011). "As regulation of steroidogenesis is one of the mechanisms involved in the development of castration-resistance prostate cancer, we wanted to study expression and regulation of PBX3 in prostate cancer." (PMID 21548940, 2011). "A Pearson's chi-squared test was preformed showing a significant difference (p < 0.001) between the PBX3 expressions in benign compared to malignant prostate cancer tissue." (PMID 21548940, 2011). "The presented results show that androgen regulates PBX3 expression via Let-7d in the prostate cancer cell lines tested." (PMID 21548940, 2011). "This study shows that PBX3 is post-transcriptionally regulated by androgen in prostate cancer cell lines." (PMID 21548940, 2011). "In light of this we wanted to investigate the possible involvement of androgen regulation of PBX3 expression in prostate cancer." (PMID 21548940, 2011). "We demonstrate that PBX3 is up-regulated in prostate cancer and post- transcriptionally regulated by androgen through Let-7d." (PMID 21548940, 2011). "PBX3 expression is positively correlated with the malignancy degree of prostate cancer." (PMID 35342419, 2022). "In prostate cancer, expression of PBX3 was found to be regulated by androgen and Let-7d." (PMID 25875009, 2015). "Future work will show whether PBX3 has a potential role as a biomarker or drug target in prostate cancer as shown in other types of cancer." (PMID 21548940, 2011). "Whereas Let-7d expression was reduced in prostate cancer, increased expression of PBX3 was observed in malignant versus benign prostate tissue by immunohistochemical staining of prostate specimens with an anti human PBX3 specific monoclonal antibody." (PMID 21548940, 2011). "The regulatory pathways SOX5-NEDD4L/PBX3, miR429-GNAQ/ANLN—RHOA, and miR429-ANLN—KIF11 may participate in the progression of the androgen-independent phenotype in prostate cancer." (PMID 29324665, 2018). "In addition, PBX3 enhances EMT and maintains an aggressive phenotype in prostate cancer." (PMID 38528641, 2024). "In this study, we show that PBX3 is post-transcriptionally regulated by androgen in prostate cancer cells and that the effect might be independent of the androgen receptor." (PMID 21548940, 2011).
acute myeloid leukemia (11 papers, 2014 to 2025). Acute myeloid leukemia (AML) is a group of neoplasms arising from precursor cells committed to the myeloid cell-line differentiation. "As a tumor suppressor, miR-516a-5p targets several genes, including histone cluster 3, H2a, circ MYC proto-oncogene, BHLH transcription factor, and PBX homeobox 3 in non-small cell lung cancer, acute myeloid leukemia, and HCC." (PMID 40996984, 2025). "One study showed that PBX3 is a potential pathologic cofactor of HOXA9 involved in cytogenetically abnormal acute myeloid leukemia (CA-AML), particularly MLL-rearranged AML." (PMID 30154863, 2018). "The PBX3 protein was also found to be a critical cofactor of HOXA9 in leukemogenesis, and targeting of the interaction between the two proteins was deemed to be a feasible strategy to treat acute myeloid leukemia with PBX3 gene overexpression." (PMID 25875009, 2015). "These include histone methylation in promoter and enhancer regions of PBX3, as well as DNA methylation as revealed by a significant increase in PBX hypomethylation in CBFP-MYH11-rearranged acute myeloid leukemia (AML)." (PMID 32069812, 2020). "Pre-B-cell leukemia homeobox 3 (PBX3) is a dominant cofactor in the PBX family, which can increase DNA-binding/transcriptional activity of homeobox (HOX) proteins, and its aberrant overexpression is required for the induction and maintenance of resistant acute myeloid leukemia." (PMID 32047817, 2020). "Since KMT2A‐r acute myeloid leukemia (KMT2A‐r‐AML) is characterized by the overexpression of HOXA/MEIS1/PBX3 homeobox genes, tackling the interactions of MEIS1/PBX3 may offer a promising therapeutic approach for treating these AML subtypes." (PMID 39428967, 2024). "For instance, TET1 has been considered as a critical oncogenic epigenetic regulator in acute myeloid leukemia (AML), which plays its role by promoting the expression of oncogenic targets, including HOXA9, MEIS1 and PBX3, and suppressing the expression of tumor suppressor miR-22." (PMID 34957093, 2021).
glioma (11 papers, 2017 to 2024). A benign or malignant brain and spinal cord tumor that arises from glial cells (astrocytes, oligodendrocytes, ependymal cells). "Our study demonstrated that the expression level of PBX3 is related to the prognosis of glioma patients, and the high expression of PBX3 is associated with poor prognosis and is a high-risk factor." (PMID 38324550, 2024). "The purpose of this study is to explore the possible prognostic value of PBX3 in gliomas and the underlying role of PBX3 in gliomas." (PMID 38324550, 2024). "This shows that PBX3 is associated with tumor progression and has a certain prognostic value in patients with glioma." (PMID 38324550, 2024). "Collectively, these results indicated that PBX3 is associated with mesenchymal transition in gliomas." (PMID 30016974, 2018). "By analyzing the expression level of PBX3 in 57 glioma cell lines from CCLE database, it was found that the expression of PBX3 was increased in glioma cell lines." (PMID 38324550, 2024). "The expression of PBX3 was observably upregulated in full-grade gliomas, LGG and GBM than that in normal tissues." (PMID 38324550, 2024). "In our previous studies, we found that PBX3 is highly expressed in gliomas, and promote glioma cell proliferation and inhibits apoptosis." (PMID 38324550, 2024). "The expression level of PBX3 in glioma tissues and glioma cells, and its correlation with clinical features were analyzed by data from TCGA, GEPIA, CGGA and CCLE." (PMID 38324550, 2024). "In TCGA and CGGA database, the OS (Overall survival time) of PBX3 high expression group was shorter than that of low expression group in full-grade gliomas." (PMID 38324550, 2024). "In our study, we found that PBX3 was highly expressed in glioma tissued by analyzing data from TCGA and GTEx databases." (PMID 38324550, 2024). "The expression of PBX3 in recurrent glioma patients was significantly higher than that in primary glioma patients, and the expression of PBX3 was increased with the increase of recurrence times." (PMID 38324550, 2024). "The expression of PBX3 was higher in IDH wildtype glioma patients than Isocitrate Dehydrogenase (IDH) mutant, and the prognosis of IDH wildtype is worse than IDH mutant type." (PMID 38324550, 2024). "First, we analyzed the expression of PBX3 in glioma tissue, the relationship between PBX3 and glioma patient’s clinical characteristics, and the prognostics value of PBX3 by TCGA, CGGA and GEPIA database." (PMID 38324550, 2024). "The study explored the relationship between PBX3 expression and glioma via bioinformatics, and needed further study with function and mechanism of PBX3 by a range of vivo and vitro experiments." (PMID 38324550, 2024). "The expression level of PBX3 in glioma patients age≥55 years was significantly higher than that in patients age <55 years." (PMID 38324550, 2024). "Herein, the relationship between the expression level of PBX3 and glioma was investigated from the perspective of bioinformatics." (PMID 38324550, 2024). "In TCGA database, the PFI (Progression-free interval) of PBX3 high expression group was shorter than that of low expression group in full-grade gliomas." (PMID 38324550, 2024). "At the same time, it is found that the expression level of PBX3 in glioma patients with 1p19q-codel deletion is significantly lower than that non-codel according to CGGA database." (PMID 38324550, 2024). "The expression of PBX3 in recurrent gliomas is significantly higher than that in primary gliomas, indicating that PBX3 can be used as a tumor marker to predict glioma recurrence." (PMID 38324550, 2024). "Based on TCGA and CGGA databases, the expression of PBX3 increased with the increase of glioma histologic-grade." (PMID 38324550, 2024). "The results showed that PBX3 was highly expressed in gliomas and its expression increased with the increase of malignancy." (PMID 38324550, 2024).
glioma (continued). "Previous studies have shown that PBX3 is upregulated in multiple tumors, including colon, liver, gastric, and cervical cancers, as well as myeloma and glioma 18, 21, 24, 42-44." (PMID 37781025, 2023). "Both let-7b and miR-98 decrease migration of glioma cells by binding to PBX3 mRNA 3′ UTR to decrease PBX3 expression." (PMID 37370851, 2023). "Overexpression of HOST2 promoted the growth and invasion of glioma cells by upregulating PBX3 via sponging let‐7b." (PMID 35068042, 2022). "PBX3 also promotes a mesenchymal phenotype in glioma cells through a positive feedback pathway involving MEK, ERK1/2, LIN28, and miR-let-7b." (PMID 32069812, 2020). "On the basis of the mesenchymal promoting role of PBX3 in glioma, we focused on migration and invasion assays." (PMID 30016974, 2018). "As expected, PBX3 overexpression promoted glioma migration and invasion, while PBX3 downregulation inhibited glioma migration and invasion." (PMID 30016974, 2018). "Our demonstrations that PBX3 is upregulated in mesenchymal gliomas compared with proneural gliomas and that it positively correlated with several mesenchymal markers highlight the significance of PBX3 in mesenchymal transition." (PMID 30016974, 2018). "We chose four mesenchymal transition markers (N-cadherin, ZEB1, Slug, and CD44) from the gene list identified by GSEA, which are reported to be involved in glioma mesenchymal transition, and analyzed the relationship between these markers and PBX3 expression." (PMID 30016974, 2018). "Results showed that PBX3 expression was increased in mesenchymal gliomas compared with proneural gliomas." (PMID 30016974, 2018). "Noting that three of the four dominant hubs exhibit protein interactions with a number of glioma-related genes, as well as the presence of several glioma-related genes in PBX3’s neighborhood, we mapped out their immediate network." (PMID 28957313, 2017). "Luciferase reporter assays identified miR-320 directly blinds to the 3′ UTR of PBX3 in glioma cells." (PMID 28934982, 2017). "Luciferase reporter assay was performed to verify the interaction between miR-320 and its targeting sequence in the 3′ UTR of PBX3 in glioma cells U87 and U251." (PMID 28934982, 2017). "MiR-320 and PBX3 expression in glioma tissues and adjacent healthy tissues was determined using qRT-PCR." (PMID 28934982, 2017). "The results showed miR–320 was significantly reduced in glioma tissues in comparison with that of adjacent healthy tissues, while PBX3 expression was detected to be significantly increased in glioma tissues." (PMID 28934982, 2017). "Western blot analysis also showed that PBX3 protein expression was significantly increased in glioma tissues compared with adjacent health tissues." (PMID 28934982, 2017). "In summary, our current data demonstrated that miR-320 is downregulated in glioma tissues and inversely correlates with PBX3 expression." (PMID 28934982, 2017). "The result reveals that PBX3 might acts as a crucial regulatory role in glioma occurrence and progression." (PMID 38324550, 2024). "However, the effect of PBX3 expression on the prognosis of gliomas and the molecular mechanism of its involvement in the occurrence and development of gliomas need to be further studied." (PMID 38324550, 2024). "Related studies have reported that PBX3 is highly expressed in glioma tissues." (PMID 38324550, 2024). "Let-7 also targets pre-B-cell leukemia homeobox 3 (PBX3) in glioma, a protein which mediates transforming growth factor β (TGF-β) signaling, driving the expression of genes that increase migration—N-cadherin (N-cad), zinc finger E-box-binding homeobox 1 (ZEB1), SNAI2, and CD44." (PMID 37370851, 2023). "Overexpression of miR‐98 inhibited glioma cell invasion and migration by directly targeting PBX3." (PMID 35068042, 2022).
glioma (continued). "Silencing PBX3 in glioma cells has been shown to reduce proliferation both in vitro and in vivo, and targeting of PBX3 by miR-98 reduced invasion and migration of glioma cells in an orthotopic model." (PMID 32069812, 2020). "Taken together, the results indicate miR-320 may suppress glioma cell growth through targeting PBX3 and regulating MAPK pathway." (PMID 30765768, 2019). "Having demonstrated that PBX3 is upregulated in mesenchymal gliomas and correlated with mesenchymal markers, we wondered whether PBX3 is required for maintenance of mesenchymal phenotype of GBM cells." (PMID 30016974, 2018). "We found that PBX3 expression levels positively correlated with glioma mesenchymal markers." (PMID 30016974, 2018). "As PBX3 regulates LIN28/let-7b axis, we wondered whether PBX3 regulates let-7b targets in glioma cells." (PMID 30016974, 2018). "In the present research we identified PBX3 was regulated by miR-320 in glioma cells." (PMID 28934982, 2017). "We identified PBX3 was regulated by miR-320 in glioma cells." (PMID 28934982, 2017). "Taken together, the results presented indicated miR-320 may suppress glioma cell growth through targeting PBX3 and regulating MAPK pathway." (PMID 28934982, 2017). "In this research, we found that PBX3 was overexpressed in glioma tissues and was regulated by miR-320, suggested PBX3 may participate in the glioma inhibition function of miR-320." (PMID 28934982, 2017). "MiR-320 downregulation and PBX3 upregulation was found in glioma tissues." (PMID 28934982, 2017). "Glioma-associated nodes in the neighborhood of FOXO1, CARHSP and PBX3." (PMID 28957313, 2017). "We find that in the PIN, both PBX3 and CARHSP1 are indirectly connected to each other (as well as several of their other neighbors in the CSD-network) through the intermediary of TRAF1, whose overexpression is also associated with the emergence of glioma." (PMID 28957313, 2017). "The substantial presence of known glioma-associated genes in the neighborhood of FOXO1, PBX3 and CARHSP1 may indicate the additional presence of genes with currently unidentified roles in glioma." (PMID 28957313, 2017). "PBX3 knockdown significantly suppressed Raf-1 phosphorylation, suggesting PBX3 might aggravate glioma through promoting the activation of Raf-1, and subsequent Raf-1 mediated MAPK cascade and apoptosis inhibition." (PMID 28934982, 2017). "PBX3 might be an important molecular mechanism for the occurrence of gliomas." (PMID 38324550, 2024). "However, PBX3 potential involvement in gliomas remains to be explored." (PMID 38324550, 2024). "PBX3 may be involved in the occurrence and development of glioma, and has potential reference value for the early diagnosis and prediction of prognosis of glioma." (PMID 38324550, 2024). "The expression of PBX3 increased with the increase of pathological grade of glioma, this unearthed that PBX3 might sever as a possible molecular marker for predicting the degree of glioma malignancy." (PMID 38324550, 2024). "In addition, PBX3 knockdown inhibits MAPK pathway activation in glioma cells." (PMID 30765768, 2019). "This study aimed to verify whether miR-320 influences glioma cells growth through regulating PBX3." (PMID 28934982, 2017). "Overexpression of miR‐320 inhibited glioma cells proliferation, and induced cell cycle arrest and apoptosis by suppressing the MAPK signalling pathway via targeting PBX3." (PMID 35068042, 2022). "Specifically, PBX3 knockdown significantly reduced the increased phosphorylation level of Raf-1, p38, and ERK1/2 in glioma cells." (PMID 34006845, 2021). "Hence, we speculated that PBX3 might also promote glioma by activating MAPK/ERT pathway." (PMID 28934982, 2017). "Another study revealed that PBX3 knockdown inhibited the MAPK signalling pathway by downregulating the expression of phosphorylated Raf‐1, p38 and ERK1/2, leading to proliferation inhibition and apoptosis promotion in glioma." (PMID 35068042, 2022).
glioma (continued). "Twenty-four human glioma and paired adjacent nontumorous tissues were collected for determination of miR-320 and PBX3 expression using RT-qPCR and western blot assays." (PMID 28934982, 2017). "The findings suggested miR-320 and PBX3 modulated MAPK pathway may contribute to their effect on the proliferation and apoptosis of glioma cells." (PMID 28934982, 2017). "MiR-320 may suppress glioma cells growth and induced apoptosis through the PBX3/Raf-1/MAPK axis, and miR-320 oligonucleotides may be a potential cancer therapeutic for glioma." (PMID 28934982, 2017). "The results suggested miR-320 might functions through the PBX3/Raf-1/MAPK axis, and miR-320 oligonucleotides might be a potential cancer therapeutic for glioma." (PMID 28934982, 2017). "However, the expression level of PBX3 correlation with clinical features, and the correlation between PBX3 and the prognosis of gliomas has not been studied." (PMID 38324550, 2024). "To further investigate the functions of PBX3 in glioma, we performed GSEA using TCGA data, GSEA showed that regulation of NOS1 pathway, CK1 pathway, HDAC pathway, Phosphatidylinositol system, Neurotransmitter receptor complex were differentially concentrated in PBX3 high expression phenotype." (PMID 38324550, 2024). "To confirm our hypothesis that PBX3 promotes glioma mesenchymal transition and then triggers migration and invasion via activating LIN28/let-7 axis, we first measured the expression of LIN28 and let-7 upon PBX3 overexpression." (PMID 30016974, 2018). "However, no data exist concerning the role of PBX3 in the progression of glioma." (PMID 28934982, 2017).
glioblastoma (8 papers, 2018 to 2024). The most malignant astrocytic tumor (WHO grade IV). "The migration and invasion of glioblastoma cells is triggered by PBX3/MEK/ERK1/2/LIN28/let-7b." (PMID 33402862, 2020). "In vivo Pbx3 suppression resulted in a reduced invasion of glioblastoma." (PMID 33402862, 2020). "The Pbx3 mRNA and protein content is higher in glioblastoma cells." (PMID 33402862, 2020). "This is true especially for primary glioblastoma, since in the recurrent forms it is downregulated and, consequently, stimulates Kirsten rat sarcoma virus (K-RAS), PBX homeobox 3 (PBX3), and matrix metallopeptidase 11 (MMP11) with the result of a promotion in cell migration and invasion." (PMID 37511303, 2023). "Some genes that were topmost DE in glioblastoma nuclei include RMST, ID4 and PBX3." (PMID 36865335, 2023).